IL10 (interleukin 10)
Diseases named in the same sentence as IL10 in open-access papers (continued):
Sharing a sentence is not in itself a finding about the gene and the disease.
infection (continued). "Moreover, IL-4Rα -deficient and IL-4Rα sufficient BMDCs produced similar levels of IL-12p70 and IL-10 during infection hence suggesting that IL-4-mediated DC instruction was not impaired in CD11ccreIL-4Rα-/lox." (PMID 35154068, 2021). "However, anti-inflammatory cytokine IL-10 exerted essential functions to maintain tissue homeostasis during infection and inflammation through restriction of excessive inflammatory responses and promotion of tissue repairing mechanisms." (PMID 33519783, 2020). "Besides, the IL-10 belongs to an anti-inflammatory cytokine and can inhibit the production of nitric oxide and activity of macrophages and Th1 cells during infection." (PMID 32670257, 2020). "Elevated serum IL-10 levels may indicate signs of immunodepression and infection contributing to poor outcome after SAH." (PMID 32106601, 2020). "The age of animals whose monocytes had higher IL-10 transcription post infection than mock infection was significantly lower at 3 hpi and 6 hpi compared to 9 hpi, when examined by univariate analysis (3 hpi: t = 4.054, p < 0.001, 6 hpi: t = 4.054, p < 0.001, 9 hpi: t = 2.255, p = 0.185)." (PMID 33121170, 2020). "Similarly, the concentrations of both IL-4 and IL-10 increased during infection and decreased after co-treatment with Alb and Sch B." (PMID 32635653, 2020). "Our results suggested that significant increase in IL‐4 and IFN‐γ productions and inhibited level of IL‐10 might enhance the protective immune response against the infection of H contortus." (PMID 32043596, 2020). "In conclusion, downregulation of NHERF1 increased anti-inflammatory IL-10, and reducing NHERF1 expression could be a potential therapeutic strategy to reduce the risk of infection/inflammation associated with PTB." (PMID 33092043, 2020). "Therefore, mice were treated with an IL-10 neutralizing antibody or isotype control at the time of infection with WT A. baumannii mixed with killed WT or killed Tn5A7 grown in the presence of kanamycin." (PMID 32168364, 2020). "In addition, in children with submicroscopic infections, IL-12p70 correlated negatively with IL-10 (r = -0.52, p = 0.012), whereas, granzyme B correlated positively with IL-4 (r = 0.62, p = 0.002)." (PMID 33281757, 2020). "In this respect, we have reported before that MIF plays a key role in T. congolense infection associated pathogenicity and we demonstrated here that MIF levels were significantly upregulated in TgAlbCre-IL10-/- mice during later stages of infection both systemically and in the liver." (PMID 32012211, 2020). "Together, these results indicate that endosomal TLRs were the primary mediators of IL-10 secretion in response to Δhly infection in mice, but that TLR2 may also contribute to induction of IL-10." (PMID 32634175, 2020). "Moreover, when evaluating DCs obtained from a mouse with a silenced TLR4 and infected with hMPV, the cytokines induced by the infection, such as IL-6, IL-10, CCL5, and IFN-β, were also decreased." (PMID 32765522, 2020). "Also, levels of granzyme B were decreased in children with either microscopic or submicroscopic infections compared to uninfected controls whilst levels of IL-10 and IL-12p70 were comparable between infected and uninfected children." (PMID 33281757, 2020). "We found that 11g-treated C. albicans could increase the secretion of TNF-α, IL-10, IL-12/23 p40, and IL-6 in macrophages after 6 h post-infection." (PMID 32695076, 2020). "In line with their discovery, we find that CXCR3+ Tregs produce more IL‐10 than CXCR3− Tregs, implying that CXCR3+ Tregs may secrete IL‐10 to modulate the infection‐induced inflammation." (PMID 33014369, 2020). "Further, in concordance to our in vitro model, a decrease in ENaC-dependent Na+ transport could be measured in the colon of C. concisus-infected IL-10−/− mice 6 days post-infection." (PMID 31936044, 2020). "However, we observed little production of IL-10 in mock or following infection with all four strains of Lactobacillus in our study." (PMID 32925983, 2020).
infection (continued). "IL-10 is a proinflammatory cytokine, which is produced by different cells, such as Th2 cells, macrophages and monocytes, and functions as an immunoregulator during infection with bacteria, fungi and viruses." (PMID 32160226, 2020). "However, Δhly L. monocytogenes induces IL-10 secretion that is detectable four hours after infection, and likely comes from macrophages or dendritic cells, which are the first cells infected by L. monocytogenes in the spleen." (PMID 32634175, 2020). "Interestingly, serum IL-10 levels were significantly higher on day 7 in SAH patients who contracted different infections during acute treatment period of SAH." (PMID 32106601, 2020). "This perspective might also be applied to T. bryosalmonae infection: in that moderate controlled mRNA levels of il-10 indicate recovery, but overproduction is consistent with clinical infection as reported in earlier PKD studies." (PMID 32582181, 2020). "Interestingly, expression of anti-inflammatory transcripts such as transforming growth factor beta (TGF-β) and IL-10 was found to be similar between D355A and wild-type infection, while others, such as SOCS1, were found to be significantly decreased." (PMID 33262258, 2020). "These functional SNPs could increase the transcriptional activity of IL-6 and IL-10 promoter, leading to the upregulation of IL-6 and IL-10 in stress or infection." (PMID 32070384, 2020). "Nevertheless, efferocytosis with increased TGF-β and IL-10 secretion increased Mycobacterium leprae survival in macrophage-1 cells from paucibacillary leprosy patients, and it contributed to the persistence and sustained infection of the mycobacterium." (PMID 32346605, 2020). "Taken together, this correlative data suggests that the presence of IL-10-producing B cells during the early stage of infection in IgMi mouse may influence the presence or development of Treg cells in the MLN and spleen." (PMID 32778925, 2020). "A high-dose infection with T. muris induces IL-10 production in IgMi mice; however, whether similar increases in IL-10 are seen during low dose infection, where mice experience exacerbated gut pathology, is unknown." (PMID 32778925, 2020). "Notably, the mRNA levels of Tnf, Il6, Il1b, Cxcl10, and Cxcl5 were significantly increased and that of Il10 decreased in lung tissue from Ppara-/- mice, compared with Ppara+/+ mice, during Mabc infection." (PMID 32155958, 2020). "However, excessive or miss-timed IL-10 production can inhibit a protective pro-inflammatory response leading to chronic and often fatal infection." (PMID 32425944, 2020). "Downregulation of NHERF1 increased anti-inflammatory mediator IL-10, indicating that reducing NHERF1 expression could be a potential therapeutic strategy to reduce the risk of infection/inflammation associated with PTB." (PMID 33092043, 2020). "The addition of DATs during WT Mtb infection recapitulated our findings of decreased inflammatory cytokine production in epithelial cells and yielded increased IL-10 production by macrophages, both supporting what was observed in Δmmpl7 mutant infection in vivo." (PMID 32695111, 2020). "Hence, during the chronic stage of the infection, hepatocyte-derived IL-10 seems to be more crucial to dampen the inflammatory immune response than leukocyte-derived IL-10." (PMID 32012211, 2020). "However, keratinocytes have also been reported to secrete anti-inflammatory molecules -such as TGF-β and IL-10- upon infection with HPV and once the tumor has been established, therefore down-modulating the activation of LCs." (PMID 32765522, 2020). "Concerns arise given the suppressive role that IL-10 can exert, which may result in the incomplete control of early infection." (PMID 32545470, 2020). "Hence, upon peroral infection of hma IL10-/- mice, C. coli induced clinical signs in a TLR4-dependent fashion." (PMID 32443576, 2020).
infection (continued). "In the liver, significantly lower expression of inflammation-related genes, including IL-8 and IL-10, also could be observed in dual-transgenic tilapia at 3 h and 6 h post-infection." (PMID 32730353, 2020). "In addition, at 8 weeks and 12 weeks post-infection, significantly increased IL-10 secretion was measured in spleen tissue homogenates (2.0 to 3.3-fold)." (PMID 33075079, 2020). "We could, for example, verify that expression of IL10 or SOCS3 genes is reduced during the infection or that expression of STAT4, LAMP3, ADORA2A and BIRC3 genes peaks 6 h pi." (PMID 32070192, 2020). "Moreover, secondary drastic increase of the levels of TNF-α, IL-1β, IL-6, and IL-8, as well as elevated IL-10, was observed at the terminal phase of infection." (PMID 33553280, 2020). "One such work reported previously in case of experimentally generated parmomycin‐resistant L. donovani increased level of MRPA, MDR1 and PP2A was found in the resistant parasites than their sensitive counterparts along with increased IL‐10 production upon infection." (PMID 32031337, 2020). "Hence, upon peroral infection of hma IL10-/- mice, C. coli induced the secretion of pro-inflammatory cytokines not only in the intestinal tract, but also systemically, in a TLR4-dependent fashion." (PMID 32443576, 2020). "This is in contrast to production of IFN-γ and IL-10 that correlate with infection, suggesting that different CD4+ve subsets may be activated by C. abortus infection in sheep." (PMID 32487248, 2020). "We also hypothesise that S. Gallinarum not only reduces inflammation within these organs but also stimulates an anti-inflammatory IL-10 response, which then establishes and maintains the infection within these organs." (PMID 33076485, 2020). "il-10 has been found to be hyper expressed in several myxozoan infections of fish." (PMID 32582181, 2020). "In obese mice, IL-10 levels were higher before infection and four weeks after infection." (PMID 31923234, 2020). "IL10 displays potent anti-inflammatory and regulatory activity in most immune processes during infection, suggesting an anti-inflammatory state in fish capable of controlling the infection." (PMID 33076342, 2020). "However, a significantly reduced level of IL-10 (p < 0.05) was observed in treated group at 14 d post-infection." (PMID 32482929, 2020). "In addition, COX-2 inhibition significantly increased macrophage cell death during ExPEC XM O2:K1:H7 infection and increased the expression of anti-inflammatory cytokine interleukin-10 (IL-10)." (PMID 32362888, 2020). "Thus, the expression of IL-10 by CD4+ T cells upon primary infection with S. aureus is likely one of the factors contributing to the lack of robust long-lasting protective CD4+ T cell memory responses." (PMID 33291260, 2020). "In another study, it was shown that CD4+ T cells with an inducible regulatory phenotype (CD4+CD25+FoxP3-T-bet+CTLA4high) produced IFNγ and IL-10 in the infection of C3H/HeN mice with a lethal dose of R. conorii and that these cells suppressed proliferation and IL-2 release by CD4+ T cells in vitro." (PMID 33091016, 2020). "Immunosuppressive cytokines such as IL-10 and IL-27 have been shown to be required in the chronic phase of infection to limit excessive inflammatory cytokine production and T cell proliferation, both of which can lead to fatal immunopathology in mice lacking IL-10 or IL-27 signaling." (PMID 31978191, 2020). "Accordingly, we showed that only CCHFV infection of moDCs induced a significant production of IL-6, IL-10 and TNF-α in comparison to the non-pathogenic HAZV." (PMID 33232320, 2020). "The levels of IL-10 were significantly elevated between 7 dpi and 30 dpi, were restored at 60 dpi and peaked at 11 dpi, 30 dpi, and 30 dpi in the low-dose, middle-dose, and high-dose infection groups, respectively." (PMID 32085808, 2020).
infection (continued). "Hence, intraperitoneal NAP application did not affect colonization efficiencies of C. jejuni upon peroral infection of secondary abiotic IL-10−/− mice." (PMID 32466564, 2020). "Finally, the number of Ly6Clow patrolling monocytes, which were documented to attenuate tissue injury, significantly dropped in TgAlbCre-IL10-/- mice at later infection stages." (PMID 32012211, 2020). "Furthermore, the expansion of CD4+ FoxP3+ T cells in lymphoid organs of mice with chronic T. canis infection, along with the higher levels of IL-10 in spleen and sera, support their role in the host systemic regulatory response to the infection." (PMID 32268573, 2020). "Similarly, experimental infection with A. suum suppressed lipopolysaccharide (LPS)-induced inflammation in mice through mechanisms mediated by Tregs, regulatory IL-10 and TGF-β." (PMID 32268573, 2020). "Notably, during infection of TLR7-deficient mice, plasma cytokines were elevated for most inflammatory cytokines but attenuated for IL-10, indicating the existence of a TLR7-independent pathway promoting inflammatory cytokine secretion." (PMID 33202596, 2020). "We measured TNF-α, IL-6, IFN-γ, IL-17A and IL-10 after an experimental intravenous infection with S. suis serotype 2 in vivo, and analyzed whole blood, peripheral blood mononuclear cells (PBMC) and separated leukocytes to identify the cytokine-producing cell type(s)." (PMID 31947746, 2020). "In addition, regulatory T cells and the production of IL-10 were significantly enhanced, which is also observed in the initial phase of the infection in C57BL/6 mice." (PMID 33091016, 2020). "IL-10 can up-regulate endogenous anti-cytokines and down-regulate pro-inflammatory cytokine receptors to dampen uncontrolled production of inflammatory cytokines and excessive inflammation during infection." (PMID 32106612, 2020). "Moreover, Nc-Spain7 infection induced lower ROS production, IL10 and IL12B expression by MØs than Nc-Spain1H infection, which also resulted in decreased IFN-γ release by activated lymphocytes." (PMID 32711550, 2020). "The depressed IL-10 levels during infection in androgenized mice may hinder the adoption of M2b or M2c phenotypes, restraining kidney macrophages in a prolonged M2a state." (PMID 32849562, 2020). "Hence, C. coli was able to colonize the gastrointestinal tract of aged conventional IL-10-/- mice following peroral infection but with varying efficiencies." (PMID 32664563, 2020). "In terms of parasite control, only the joint effect of cytokines, but not their isolated effects, could be evaluated in the present study, but the results suggest that infection control may involve a balance between IL-17 and IL-10." (PMID 32966326, 2020). "The IL-10 gene expression is significantly increased at 7 days post infection in MLNs and CLNs." (PMID 33324583, 2020). "Furthermore, increased levels of circulating IL-10 in the CSE−/− mouse serum were found after 3 wk of infection." (PMID 32139610, 2020). "IL-10, greater in patients at T0 than in controls, promotes the immune responses and the integrity of tissue epithelial layers facilitating the tissue-healing process after infection or inflammation." (PMID 32451455, 2020). "It has been reported that N. brasiliensis regulates macrophage cytokine production, which may contribute to pathogenesis, and the production of IL-10 has also been shown to be increased after infection of mice with N. brasiliensis." (PMID 32117792, 2020). "Ducks vaccinated with inactivated R. anatipestifer plus levamisole as an adjuvant showed increased secretion of Th1-type (interferon [IFN]-γ and interleukin [IL]-2) and Th2-type (IL-4 and IL-10) cytokines and enhanced survival following challenge infection with a homologous R. anatipestifer strain." (PMID 33175869, 2020). "In contrast, IL-10 was detected in higher levels in B. microti-infected mice on days 2 and 4, however control mice had higher serum IL-10 levels 6 days after the challenge infection." (PMID 32411624, 2020).
infection (continued). "Therefore, PP2A has little effect on infection induced IL‐10 level change in Ago2Y529F‐expressing cell, as in those cells, Ago2Y529F is phosphorylation defective and therefore should not be responsive to the presence and absence of PP2A." (PMID 32031337, 2020). "Indeed, although TgAlbCre-IL10-/- mice behaved similar to WT and LysMCre-IL-10-/- mice during the early stages of infection, they succumbed much earlier to the infection coinciding with increased tissue pathogenicity." (PMID 32012211, 2020). "Even if IL–10 is not frequently studied as it is less expressed in neonates, an increased value is very suggestive for a severe infection, usually associated with multi organ damage." (PMID 33419284, 2020). "Hence, TLR4 signaling was involved in mediating C. coli-induced colonic histopathological and epithelial cell apoptosis upon peroral infection of secondary abiotic IL-10−/− mice." (PMID 33261211, 2020). "Thus, IL-10 secretion apparently represents a neuroprotective mechanism in acute TMEV-infection, whereas the suppressive effect on antiviral immunity is most likely mediated by other Treg effector functions." (PMID 32131483, 2020). "Compared with PBS group, the levels of pulmonary IFN-β, IFN-γ, and IL-10 significantly increased at 3 or 5 days post-infection in the mice administered with live (P = 0.0425, P = 0.0111, and P = 0.0400) or pasteurized A. muciniphila (P = 0.0076, P = 0.0241, and P = 0.0126)." (PMID 33603716, 2020). "COX-2 up-regulation may also benefit the host defense against ExPEC XM O2:K1:H7 infection through down-regulation of the IL-10 expression, a known anti-inflammatory cytokine, and reduction of macrophage cell death during ExPEC XM O2:K1:H7 infection." (PMID 32362888, 2020). "Similarly, Mycobacterium tuberculosis contains a TLR inhibitor, thus infection by this bacteria can aid in the recovery of EAE because it mediates the production of IL-10 by B cells." (PMID 32973780, 2020). "IL-10 protein was undetectable at 48h after BCG-p infection." (PMID 32645059, 2020). "Similarly, high levels of IL‐17A, IL‐10 and sE‐selectin were measured in patients with all endovascular infections (IE + non‐IE) vs. extravascular foci, as well as non‐IE endovascular infections vs. extravascular foci." (PMID 32082571, 2020). "Importantly, we observed increased IL-10 production in macrophages and DCs after Δmmpl7 mutant infection." (PMID 32695111, 2020). "Among these elevated cytokines in AdV 7 infected patients, all but IL-10 are either pro-inflammatory cytokines or chemokines that responsible for chemoattracting inflammation-related immune cells to the site of infection, which together contribute to the inflammatory cytokine storm in the airway." (PMID 33072092, 2020). "In fact, C. jejuni induced intestinal pro-inflammatory immune responses TLR4-dependently in secondary abiotic wildtype mice on day 14 post-infection, which also held true for secondary abiotic IL10-/- mice suffering from acute enterocolitis on day 6 upon C. jejuni challenge." (PMID 32443576, 2020). "IL-10 levels increased in the serum of WT mice upon infection with T. cruzi K98 clone." (PMID 33072115, 2020). "The general sOP profile in this NP immune network model could be characterized as pro-inflammatory, in that inflammatory markers were predicted to be overexpressed early in infection while IL10 was consistently reduced." (PMID 32595639, 2020). "Furthermore, mice treated with LA displayed elevated levels of IL-12 and IFN-γ but reduced levels of IL-10 during infection." (PMID 32482929, 2020). "The induction of IL-10 during L. amazonensis infection could explain the high amount of parasite observed at 48 h post-infection in comparison to L. infantum." (PMID 32596164, 2020).